VPS41 (VPS41 subunit of HOPS complex)
Description:
Plays a role in vesicle-mediated protein trafficking to lysosomal compartments including the endocytic membrane transport and autophagic pathways. Acts as a component of the HOPS endosomal tethering complex. This complex is proposed to be involved in the Rab5- to-Rab7 endosome conversion probably implicating MON1A/B, and via binding SNAREs and SNARE complexes to mediate tethering and docking events during SNARE-mediated membrane fusion. The HOPS complex is proposed to be recruited to Rab7 on the late endosomal membrane and to regulate late endocytic, phagocytic and autophagic traffic towards lysosomes. Involved in homotypic vesicle fusions between late endosomes and in heterotypic fusions between late endosomes and lysosomes implicated in degradation of endocytosed cargo. Required for fusion of autophagosomes with lysosomes. Links the HOPS complex to endosomal Rab7 via its association with RILP and to lysosomal membranes via its association with ARL8B, suggesting that these interactions may bring the compartments to close proximity for fusion. Involved in the direct trans-Golgi network to late endosomes transport of lysosomal membrane proteins independently of HOPS. Involved in sorting to the regulated secretory pathway presumably implicating the AP-3 adapter complex (By similarity). May play a role in HOPS-independent function in the regulated secretory pathway.
Synonyms: HVSP41; HVPS41; SCAR29; hVps41p
Tractability: Antibody: UniProt places it where antibodies can reach, with high confidence. PROTAC: ubiquitination databases record sites on it; its protein half-life has been measured.
Gene: Protein-coding gene on chromosome 7 (38,722,974 to 38,932,394, reverse strand). Ensembl gene ENSG00000006715.
Subcellular location: Endosome membrane; Late endosome membrane; Early endosome membrane; Lysosome membrane; Golgi apparatus, trans- Golgi network; Cytoplasmic vesicle, clathrin-coated vesicle; Cytoplasm, cytosol
Pathways (Reactome):
Disease: SARS-CoV-2 modulates autophagy
Gene Ontology:
Molecular function: identical protein binding; molecular adaptor activity; protein binding; protein-membrane adaptor activity; microtubule binding
Biological process: autophagosome-lysosome fusion; endosomal vesicle fusion; endosome to lysosome transport; late endosome to lysosome transport; vesicle-mediated transport; cellular response to starvation; macroautophagy; regulation of SNARE complex assembly; intercellular transport; intracellular protein transport; protein targeting to vacuole
Cellular component: AP-3 adaptor complex; clathrin complex; clathrin-coated vesicle; early endosome membrane; endosome membrane; HOPS complex; late endosome; late endosome membrane; lysosomal HOPS complex; lysosomal membrane; lysosome; cytosol; early endosome; Golgi apparatus; microtubule cytoskeleton
Genetic constraint (gnomAD): Loss-of-function variants: 56 observed, 77.43 expected, observed/expected ratio (o/e) 0.72, 90% interval 0.58 to 0.9. The upper end of that interval is the gene's LOEUF score, 0.9, which puts it in group 3 of 6, group 1 being the genes least tolerant of losing a copy. Missense variants: 567 observed, 670.94 expected, observed/expected ratio (o/e) 0.85, 90% interval 0.79 to 0.91. Synonymous variants: 225 observed, 224.92 expected, observed/expected ratio (o/e) 1, 90% interval 0.9 to 1.12.
Homologues: Orthologues: chimpanzee VPS41 (100% identical), macaque VPS41 (99% identical), rabbit VPS41 (98% identical), mouse Vps41 (97% identical), guinea pig VPS41 (97% identical), rat Vps41 (96% identical), dog VPS41 (96% identical), pig VPS41 (92% identical), zebrafish vps41 (81% identical), tropical clawed frog vps41 (80% identical), Drosophila melanogaster lt (31% identical), Caenorhabditis elegans vps-41 (24% identical).
Diseases named in the same sentence as VPS41 in open-access papers:
VPS41 is named in the same sentence as 27 diseases in open-access papers, as found by Europe PMC text mining. Sharing a sentence is not in itself a finding about the gene and the disease. The quoted sentences say what the papers report.
Dystonia (6 papers, 2021 to 2025). An abnormally increased muscular tone that causes fixed abnormal postures. "Intriguingly, recently the HOPS component VPS41 has been reported to be mutated in patients suffering from neurodegenerative conditions such as ataxia and dystonia." (PMID 41173829, 2025). "Compound heterozygous mutations in VPS41 were identified in patients with a neurodegenerative phenotype with dystonia and cerebellar atrophy." (PMID 33851776, 2021). "Naturally occurring SNPs in VPS41 have been described (T52R, T146P and A187T; Harrington etal, 2012; Ibarrola‐Villava etal, 2015), and very recently a single patient with early onset dystonia and a homozygous canonical splice site variant in VPS41 was identified (Steel etal, 2020)." (PMID 33851776, 2021). "Variants in the genes encoding for the HOPS complex have been associated with the etiopathogenesis of inherited dystonia (i.e., VPS16, VPS41, and VPS11)." (PMID 40655316, 2025). "Here, we report three patients with compound heterozygous mutations in VPS41 (VPS41S285P and VPS41R662*;VPS41c.1423‐2A>G and VPS41R662*) displaying neurodegeneration with ataxia and dystonia." (PMID 33851776, 2021). "One of our patients (Patient 1) presents a slightly different phenotype, characterized by a less severe intellectual disability and ataxia without overt dystonia, clearly indicating that the phenotypic expression of VPS41‐related disorders is variable." (PMID 33851776, 2021).
Cognitive impairment (2 papers, 2022). Abnormal cognition is characterized by deficits in thinking, reasoning, or remembering. "The overexpression of circ-Vps41 could upregulate synaptophysin (Syp), thereby promoting the synaptic plasticity and alleviating cognitive impairment in aging mice." (PMID 36533129, 2022).
Parkinson disease (2 papers, 2021 to 2025). A progressive degenerative disorder of the central nervous system characterized by loss of dopamine producing neurons in the substantia nigra and the presence of Lewy bodies in the substantia nigra and locus coeruleus. "Intriguingly, VPS41 was previously identified as neuroprotector in C. elegans and mammalian models of Parkinson’s disease (Ruan etal, 2010; Harrington etal, 2012; Griffin etal, 2018)." (PMID 33851776, 2021). "VPS41 was previously reported to confer neuroprotection in both C. elegans and mammalian models for Parkinson’s disease (Hamamichi etal, 2008; Ruan etal, 2010; Harrington etal, 2012; Griffin etal, 2018)." (PMID 33851776, 2021). "Previously, a screen for neuroprotective factors in a transgenic C. elegans model for Parkinson’s disease showed that overexpression of human VPS41 protects against α‐synuclein‐induced neurodegeneration (Hamamichi etal, 2008; Ruan etal, 2010; Harrington etal, 2012)." (PMID 33851776, 2021). "The clinical symptoms of the VPS41 patients overlap with Parkinson’s disease." (PMID 33851776, 2021). "Finally, we show that compound expression of VPS41S285P and VPS41R662* abolishes the neuroprotective effect of VPS41 in the C. elegans model of Parkinson’s disease." (PMID 33851776, 2021). "In a C. elegans model of Parkinson’s disease, co‐expression of VPS41S285P/VPS41R662* abolished the neuroprotective function of VPS41 against α‐synuclein aggregates." (PMID 33851776, 2021). "This requires the small GTPase Arl8b rather than Rab7 or AP‐3, indicating that VPS41, through different interaction partners, can trigger divergent neuroprotective mechanisms against Parkinson’s disease and Alzheimer’s disease (Griffin etal, 2018)." (PMID 33851776, 2021).
Eagle-Barrett syndrome (1 paper, 2022). "AD, MND, and MG were all associated with SNPs in VPS41 (associated with Wilms tumor) and CHRM3 (associated with Eagle-Barrett syndrome)." (PMID 35711735, 2022).
idiopathic dystonia (1 paper, 2021). "Seven (10%) patients had confirmed genetic diagnosis (including THAP1, ADCY5, VPS41, ATXN3, AFG3L2, KMT2B), 12 (18%) had acquired causes and the remainder had idiopathic dystonia." (PMID 34437382, 2021).
lysosomal disorders (1 paper, 2021). "In summary, our data imply that VPS41 patients may represent a novel class of lysosomal disorders in which lysosomes are enzymatically active, but due to delayed trafficking kinetics inefficiently reached by endocytic and autophagic cargo." (PMID 33851776, 2021).
malaria (1 paper, 2025). Malaria is a serious and sometimes fatal disease caused by a parasite that commonly infects a certain type of mosquito which feeds on humans. "Homologues for the CORVET and HOPS specific subunits VPS8 and VPS41 are not currently annotated in the malaria genome, but BLAST analysis using the VPS 41/8 domain of Tgvps8 as query identified a conserved gene with unknown function (PF3D7_0916400) sharing 48% identity." (PMID 40198740, 2025).
infection (3 papers, 2014 to 2022). The state of being infected such as from the introduction of a foreign agent such as serum, vaccine, antigenic substance or organism. "As found previously, infection with wild type S protein carrying MHV was reduced after gene silencing of RAB5, RAB7, VPS11, and VPS41 (red bars)." (PMID 25375324, 2014). "On the other hand, infection with MHV-S2′FCS was significantly diminished by downregulation of the early endosomal proteins RAB5B and RAB5C, but not of the late endosomal proteins RAB7A and RAB7B or the HOPS complex components VPS11 and VPS41 (blue bars)." (PMID 25375324, 2014). "Silencing of NSF, required for transport from early to late endosomes, or of the HOPS subunits VPS11 and VPS41, which are involved in late endosome to lysosome maturation, all resulted in severely reduced MHV infection (turquoise and light green, respectively)." (PMID 25375324, 2014).
cancer (2 papers, 2023 to 2025). A tumor composed of atypical neoplastic, often pleomorphic cells that invade other tissues. "Additionally, VPS41 generally showed non‐significant or inverse association with patient survival across various cancers, including SKCM." (PMID 40271553, 2025). "Otherwise, VPS41 restrained methuosis and autophagy in cancer." (PMID 37511481, 2023).
neurodegenerative disease (2 papers, 2021 to 2025). A disorder of the central nervous system characterized by gradual and progressive loss of neural tissue and neurologic function. "Deletion of VPS41 is embryonically lethal, and we and others have shown that mutations in VPS41 result in a severe neurodegenerative disease caused by a defect in HOPS-dependent endosome–lysosome fusion." (PMID 39907656, 2025). "We conclude that the VPS41 variants specifically abrogate HOPS function, which interferes with the TFEB/TFE3 axis of mTORC1 signaling, and cause a neurodegenerative disease." (PMID 33851776, 2021).
tumor (2 papers, 2019 to 2025). "In contrast, following genotoxic treatment of tumor cells (A375 and SiHa), there was minimal evidence of significant changes in VPS41 expression." (PMID 40271553, 2025). "VPS41 upregulation in normal skin cells following ionizing radiation contrasts with its stable expression in tumor cells, suggesting a differential response to genotoxic stress in normal versus cancerous tissues." (PMID 40271553, 2025). "On the other hand, SLC6A6 and SLC22A4 are transporters, SART3 is a tumor rejection antigen, VPS41 is involved in organelle development, SEMA4C is involved in axon guidance, and SHMT1 is an enzyme with involvement in glycine, serine, and threonine metabolism." (PMID 30973896, 2019). "Notably, VPS41 exhibited significantly different responses to genotoxic therapy in tumor cells compared to normal cells." (PMID 40271553, 2025).
VPS41 also shares sentences with these, for which no sentence is quoted: Ataxia (4 papers); neurological disorder (2); bacterial infection (1); breast carcinoma (1); Cerebellar atrophy (1); diabetes (1); insulinoma (1); Intellectual disability (1); memory impairment (1); movement disorder (1); neuroblastoma (1); Nystagmus (1); ovarian carcinoma (1); Salmonella Infections (1); skin cutaneous melanoma (1); Wilms tumor (1).